TSPAN1 (tetraspanin 1)
Diseases named in the same sentence as TSPAN1 in open-access papers (continued):
Sharing a sentence is not in itself a finding about the gene and the disease.
endometriosis (2 papers, 2021 to 2024). The growth of functional endometrial tissue in anatomic sites outside the uterine body. "TSPAN1 has been recognized as a prospective gene candidate for the screening of high-risk endometriosis, thereby facilitating the advancement of therapeutic pharmaceuticals." (PMID 38384812, 2024). "To determine the mechanism of growth and invasion of endometriosis cells in response to TSPAN1, we measured the phosphorylation of major kinases associated with cell growth and survival." (PMID 33331115, 2021). "TSPAN1 therefore has potential as a pathological marker of high‐risk endometriosis." (PMID 33331115, 2021). "Our study suggests the potential of TSPAN1 as a screening candidate for high‐risk endometriosis." (PMID 33331115, 2021). "We investigated the TSPAN1 mRNA and protein expressions using our own endometrial cells (6595 and 6866_SV40), endometriosis cells (6045_SV40 and 9585_SV40), and OCCC cells (ES‐2, TOV‐21G, OVTOKO, and OVISE)." (PMID 33331115, 2021). "The results of the current study demonstrate that AMPK activity had a tumor‐promoting function and increased endometriosis cell growth in response to TSPAN1." (PMID 33331115, 2021). "Collectively, TSPAN1 is increased when endometriosis cells are exposed to stressful environments, thus affecting the endometriosis cell growth and invasion via AMPK activation." (PMID 33331115, 2021). "While investigating genes involved in this process, we confirmed that TSPAN1 expression increases during progression from endometriosis to OCCC." (PMID 33331115, 2021). "Moreover, the stimulation of AMP-activated protein kinase (AMPK) by TSPAN1 has been shown to promote the development of endometriosis and cellular proliferation." (PMID 38384812, 2024). "To explore the function of TSPAN1, we cultured primary endometrial and endometriosis cells." (PMID 33331115, 2021). "In immortalized endometriosis cell lines, TSPAN1 overexpression enhanced cell growth and invasion." (PMID 33331115, 2021). "Furthermore, we demonstrated that TSPAN1 is involved in endometriosis cell growth through AMPK activation." (PMID 33331115, 2021). "Therefore, this study has great significance in discovering the role of TSPAN1 in the malignant transformation of endometriosis into OCCC." (PMID 33331115, 2021). "TSPAN1 was found to increase endometriosis cell growth and invasion by promoting AMPK activity." (PMID 33331115, 2021). "Moreover, our findings enable the development of drugs that can aid in preventing the transformation of endometriosis into malignant cancer by controlling TSPAN1 levels and AMPK activity." (PMID 33331115, 2021). "In addition, in this study, TSPAN1‐overexpressing endometriosis and OCCC cells had increased cell growth compared to control cells." (PMID 33331115, 2021). "Mechanistically, TSPAN1 triggered AMP‐activated protein kinase (AMPK) activity, promoting endometriosis and cell growth." (PMID 33331115, 2021). "Immunohistochemistry confirmed that TSPAN1 protein expression was higher in AtyEm and OCCC than in endometriosis." (PMID 33331115, 2021). "TMA staining showed that TSPAN1 has higher expression in AtyEm and early‐stage OCCC than in endometriosis." (PMID 33331115, 2021). "Similar to endometriosis cells, the growth rate of OCCC cell lines was delayed in response to reduced TSPAN1 expression." (PMID 33331115, 2021). "Unlike in endometriosis cells, the role of TSPAN1 is not carried out via AMPK activity in OCCC cells." (PMID 33331115, 2021). "We found that tetraspanin 1 (TSPAN1) mRNA level was significantly increased by 2.4‐ (DESeq2) and 3.4‐fold (edgeR) in AtyEm and by 80.7‐ (DESeq2) and 101‐fold (edgeR) in OCCC relative to endometriosis." (PMID 33331115, 2021). "However, in this study, TSPAN1‐overexpressing endometriosis cells did not have altered AKT and ERK activity, and their growth was promoted via AMPK activation." (PMID 33331115, 2021).
endometriosis (continued). "TSPAN1 expression was higher in OCCC cells (TOV‐21G, OVTOKO, and OVISE, but not ES‐2) than in endometrial and endometriosis cells." (PMID 33331115, 2021).
osteosarcoma (2 papers, 2021 to 2024). A usually aggressive malignant bone-forming mesenchymal neoplasm, predominantly affecting adolescents and young adults. "Consistently, Tspan1 was found to be negatively regulated by miR-491-3p, and downregulated Tspan1 attenuated the invasion and proliferation of osteosarcoma cells." (PMID 38389703, 2024). "In tongue cancer, mTORC2 downregulated miR-491-3p expression by inactivating FOXO1; while in osteosarcoma miR-491-3p functions as a tumor suppressor to attenuate the potential of growth and invasion by targeting TSPAN1." (PMID 33098307, 2021). "It was identified that miR-491-3p expression was frequently decreased in osteosarcoma tissues and osteosarcoma cell lines, which functions as a tumor suppressor to attenuate the potential of growth and invasion by targeting TSPAN1." (PMID 33098307, 2021).
prostate tumors (2 papers, 2016 to 2017). "TSPAN1 expression was decreased in more progressive prostate tumors, and it could be used to predict the early biochemical recurrence after radical prostatectomy." (PMID 27556508, 2016).
chronic hepatitis B (1 paper, 2022). "Herein, this study found that numbers of cells expressing TSPAN1 were significantly increased in AIH patients compared to PBC, chronic hepatitis B, and healthy control (P < 0.0001)." (PMID 36591302, 2022).
lymph node metastasis (1 paper, 2021). "Through the clinical-pathological analysis, we noticed the expression of TSPAN1 was significantly correlated with pathological staging and lymph node metastasis of patients." (PMID 34852709, 2021).
pharyngeal cancer (1 paper, 2020). "The metastatic cell line CCL-138 derived from a pharyngeal cancer showed the highest TSPAN1 levels." (PMID 33167355, 2020). "According to the herein presented data, we anticipate that TSPAN1 inhibition could represent a promising candidate for targeted therapy against laryngeal and pharyngeal cancers and possibly other HNSCC subsites." (PMID 33167355, 2020). "Our results uncover TSPAN1 as a key protein in HNSCC pathogenesis, particularly in laryngeal and pharyngeal cancer." (PMID 33167355, 2020). "The role of TSPAN1 on CDDP response was also explored in biopsy-derived cell lines from laryngeal and pharyngeal cancer patients." (PMID 33167355, 2020).
pharyngeal tumors (1 paper, 2020). "Secondly, TSPAN1 protein levels were analyzed by Western blot in paired samples of laryngeal and pharyngeal tumors (T) and patient-matched normal mucosa (N)." (PMID 33167355, 2020). "Thus, TSPAN1 expression was detected in ~45% (IHC) of laryngeal and pharyngeal tumors, a similar percentage to the upregulation of TSPAN1 detected at mRNA level (8 out of 16 patients) and also by Western blot (eight out of 12 patients)." (PMID 33167355, 2020). "For the first time, this study investigates the clinical and biological relevance of TSPAN1 in HNSCC, with a special focus on laryngeal and pharyngeal tumors." (PMID 33167355, 2020).
pulmonary fibrosis (1 paper, 2019). Chronic progressive interstitial lung disorder characterized by the replacement of the lung tissue by connective tissue, leading to progressive dyspnea, respiratory failure, or right heart failure. "Tetraspanin 1(TSPAN1) as a clinically relevant gene target in cancer has been studied, but there is no direct in vivo or vitro evidence for pulmonary fibrosis (PF)." (PMID 30869194, 2019).
serous ovarian carcinomas (1 paper, 2021). "Notably, TSPAN1 shows pronounced expression in serous ovarian carcinomas at FIGO stage IIIC." (PMID 34215221, 2021).
tumor (46 papers, 2003 to 2025). "C0 TSPAN1+ tumor EPCs were linked to viral life cycle, actin organization, and host interactions in GOBP, and to adherens junction, tight junction, protein processing, focal adhesion, and HPV infection in KEGG." (PMID 40777026, 2025). "Among these, TSPAN1 plays a critical role in various cancers and is associated with processes such as tumor proliferation, invasion, apoptosis, autophagy, angiogenesis, stemness, and metastasis." (PMID 40777026, 2025). "They found the expression level of TSPAN1 was positively related to the clinical stage and lymph node status of the tumor, while negatively associated with cancer cell differentiation and survival rates." (PMID 34222025, 2021). "C0 TSPAN1+ tumor EPCs promoted paracrine and autocrine interactions with fibroblasts, leading communication." (PMID 40777026, 2025). "Analysis revealed that C0 TSPAN1+ tumor EPCs played multiple roles—senders, receivers, mediators, and influencers." (PMID 40777026, 2025). "By analyzing TF expression and regulatory activity in different tumor cell subtypes, we determined that the M1 module mainly regulated the C0 TSPAN1+ tumor EPCs." (PMID 40777026, 2025). "TSPAN1 likely influenced tumor progression within the TME by regulating the interaction between tumor endothelial progenitor cells and fibroblasts." (PMID 40777026, 2025). "C0 TSPAN1+ tumor EPCs showed a particularly strong effect on fibroblasts compared to other cell types." (PMID 40777026, 2025). "Conversely, other genes were highly expressed and broadly distributed in PCa sections, with TFF3 and TSPAN1 concentrated in tumor regions." (PMID 40161494, 2025). "The identification of TSPAN1 as key biomarkers provided insight into tumor biology and potential therapeutic targets." (PMID 40777026, 2025). "Fibroblasts acted as receivers, mediators, and influencers in interactions with C0 TSPAN1+ tumor EPCs." (PMID 40777026, 2025). "We identified five tumor EPC subtypes using cell markers: C0 TSPAN1+, C1 AKR1B10+, C2 TOP2A+, C3 PTPRC+, and C4 LRMP+." (PMID 40777026, 2025). "The circle graphs quantified these interactions, with C0 TSPAN1+ tumor EPCs acting as the signaling source and target." (PMID 40777026, 2025). "Based on the optimal TSPAN1+ tumor EPCs score cut-off, TCGA participants were divided into high and low TTRS (TSPAN1+ tumor EPCs risk score) groups." (PMID 40777026, 2025). "High communication between C0 TSPAN1+ tumor EPCs and fibroblasts was observed with the MDK-NCL and MDK-LRP1 ligand-receptor pairs, and a chord diagram further validated these interactions." (PMID 40777026, 2025). "Tspan1, Tspan11, Tspan13, Tspan28, Tspan29, and Tspan30 have been identified as biomarkers for tumor diagnosis and prognosis, while Tspan8, Tspan24, and Tspan27 show potential as biomarkers." (PMID 38649381, 2024). "On the other hand, several studies also found the suppressive effects of miR638 on the invasiveness of tumor cells by targeting tetraspanin-1 or phospholipase-C, or by regulating the wnt/b-catenin pathway." (PMID 39518968, 2024). "Blocking TSPAN1 demonstrated encouraging in vivo results, leading to impaired tumor growth, EMT acquisition, and metastasis spreading." (PMID 37065869, 2023). "The expression of LY6D, SCNNA1 and TSPAN1 was higher in tumor tissues than in normal tissues, whereas the expression of RECQL, PEG10 and SEPT3 was lower in tumor tissues than in normal tissues." (PMID 37274269, 2023). "TSPAN1 is a transmembrane protein that has been reported to be elevated in many human cancers and to be involved in tumor progression 8-12." (PMID 35154458, 2022). "TSPAN1 has been reported to be elevated in many human cancers and to be involved in tumor progression 8-12." (PMID 35154458, 2022). "In contrast, mEPCs from CC1 and GBC11 displayed upregulation of multiple tumor-specific genes (e.g., S100P, TSPAN1, CEACAM5)." (PMID 36198671, 2022).
tumor (continued). "We further noticed the expression of TSPAN1 in tumor tissues was correlated with the survival rates of patients." (PMID 34852709, 2021). "Then the patients were divided into TSPAN1 high and low expression groups according to the staining levels of TSPAN1 in tumor tissues." (PMID 34852709, 2021). "Since MCF-7 cell line was a metastatic cell line, we used it in the in vivo assays, and found the effects of TSPAN1 on tumor growth in vivo." (PMID 34852709, 2021). "Four genes were associated with the tumor stage, including solute carrier family 6 member 14 (SLC6A14), polypeptide N-acetylgalactosaminyltransferase 5 (GALNT5), tetraspanin 1 (TSPAN1), and islet amyloid polypeptide (IAPP)." (PMID 34591244, 2021). "Tumor sizes were significantly lower in the tumors generated from TSPAN1-depleted cells compared to those formed by control cells." (PMID 33167355, 2020). "Further studies in which the expression of MMP2 in isolated CTC is evaluated, in parallel to TSPAN1, are required to confirm the potential role of TSPAN1 in migration of cancer cells via blood to distinct tumor metastatic sites." (PMID 35582043, 2020). "Of note, high TSPAN1 levels were also observed in some normal tissues comparable to the matched tumor." (PMID 33167355, 2020). "TSPAN1 overexpression was detected in eight out of 12 tumor samples compared to the normal counterparts." (PMID 33167355, 2020). "Firstly, the expression of TSPAN1 was analyzed at mRNA level in 16 biopsies of tumor tissue and patient-matched normal mucosa." (PMID 33167355, 2020). "Zhang J and the colleagues have found that miR-638 was down-regulated and functioned as a tumor suppressor by inhibiting TSPAN1 in human CRC." (PMID 28947960, 2017). "Studies in gastric, colonic, and cervical cancer have shown that TSPAN1 can promote tumor cell proliferation and invasion in vitro and its expression is elevated in these primary tumor tissues of human." (PMID 27556508, 2016). "After adjustment for age, gender, tumor size, TNM stage and grading, a Cox multivariate analysis indicated that high TSPAN1 expression is an independent risk factor for survival (adjusted HR = 2.818, 95% CI = 1.355-5.862, p = 0.006)." (PMID 25301729, 2014). "Taken together, our current data demonstrate that miR-638 functions as a tumor suppressor in human CRC by inhibiting TSPAN1, and that TSPAN1 is a potential prognostic factor for CRC." (PMID 25301729, 2014). "Sj-TSP-#2 shared 29% with Tetraspanin-1 (Tspan-1) [Genbank: XP_002577444.1], which is a tumor proliferation-related protein from the TM4SF." (PMID 21958506, 2011). "TSPAN1 is overexpressed in GC where it correlates negatively with the degree of tumour differentiation and survival, and positively with depth of invasion and lymph node involvement." (PMID 21284875, 2011). "Specifically, TSPAN1 might have modulated intercellular signaling pathways, thereby affecting the function of both CAFs and tumor endothelial progenitor cells." (PMID 40777026, 2025). "TSPAN1 might affect tumor invasion and metastasis by modulating the expression of matrix metalloproteinases, which involves EPCs’ function." (PMID 40777026, 2025). "The findings revealed significant communication between C0 TSPAN1+ tumor EPCs and fibroblasts." (PMID 40777026, 2025). "The combined evaluation of TSPAN1 with other molecules such as PTEN may improve predictions of tumor invasiveness." (PMID 40777026, 2025). "The tumor-promoting capacity of TSPAN1 was markedly abolished by FAM110A knockdown." (PMID 35154458, 2022). "So, these results showed that miR454 could play a tumor suppressor role in PC, whereas TSPAN1 and FAM83A could behave as promoters of neoplastic growth and progression." (PMID 36558998, 2022). "The TSPAN1 protein levels were considerably higher in tumor tissues relative to healthy tissues." (PMID 33188589, 2021).
tumor (continued). "TCGA data showed the significant up-expression of TSPAN1 in CRC tumor compared with normal tissue." (PMID 33968341, 2021). "Finally, immunohistochemical staining results suggested that the TSPAN1 protein levels in the Human Protein Atlas were significantly higher in tumor tissue than in normal tissue." (PMID 33188589, 2021). "The results showed that tumor growth in the TSPAN1 siRNA group was slower than that of the control." (PMID 34852709, 2021). "TSPAN1 has recently been demonstrated to be elevated in human primary PDAC tumor cells and cell lines, in addition to high-grade cervical intraepithelial neoplasia and advanced cervix carcinoma, lung cancer, colon cancer, breast cancer, and squamous cell carcinoma." (PMID 35582043, 2020). "The recovery of spiked TSPAN1+ tumor cells was high with limited contamination by leukocytes." (PMID 35582043, 2020). "However, several studies have reported that miR-638 can also function as tumor suppressor miRNAs, its loss of function leading to proliferation, EMT, migration and invasion of CRC by upregulating SOX2 and TSPAN1 proteins." (PMID 30469518, 2018). "In addition, increased TSPAN1 immunoreactivity correlated with poor overall survival (Log-rank = 7.272, p = 0.007), poor tumor differentiation (Spearman r = 0.184, p = 0.026) and high TNM stage (Spearman r = 0.170, p = 0.040)." (PMID 25301729, 2014). "TSPAN1, a new member of the tetraspanin family, is a recently discovered tumor-related gene." (PMID 25301729, 2014). "By modulating the ECM composition and structure, TSPAN1 could directly affect the function of tumor endothelial progenitor cells, thereby influencing tumor angiogenesis and contributing to the overall progression of the tumor." (PMID 40777026, 2025). "TSPAN1 may promote tumor angiogenesis by influencing EPCs in the TME." (PMID 40777026, 2025). "TSPAN1 can activate PI3K/AKT and EGFR/MAPK/ERK signaling pathways, enhancing tumor cell proliferation." (PMID 40777026, 2025). "We further investigated and analyzed the EPCs subtypes, categorizing them into C0 TSPAN1+ Tumor EPCs, C1 AKR1B10+ Tumor EPCs, C2 TOP2A+ Tumor EPCs, C3 PTPRC+ Tumor EPCs, and C4 LRMP+ Tumor EPCs." (PMID 40777026, 2025). "In the tumor compartment, several tetraspanins (CD9, CD151, TSPAN1, TSPAN3, TSPAN8, and TSPAN13) were specifically overexpressed, suggesting their involvement in tumor growth and proliferation in stage 4 primary CC." (PMID 38255741, 2024). "CD9, CD151, TSPAN1, TSPAN3, TSPAN8, and TSPAN13 displayed specific overexpression in the tumor compartment, indicating potential roles in tumor growth." (PMID 38255741, 2024). "Among these genes, the expression of LY6D, SCNNA1, TSPAN1 and RECQL was significantly higher in tumor tissues than in normal tissues, but the expression of TSPAN1 and RECQL was significantly lower in tumor tissues than in normal tissues." (PMID 37274269, 2023). "Some tetraspanins, such as TSPAN15, can enhance tumor cell proliferation ability, while other family members, such as CD9, CD63, TSPAN1, TSPAN7, and TSPAN31, can antagonize apoptosis and facilitate tumor cell survival." (PMID 34540692, 2021). "TSPAN1 (NET-1) is identified to express in epithelial cell lines and multiple tumor cell lines including cervical carcinoma, lung carcinoma, squamous carcinoma, colon carcinoma, and breast carcinoma." (PMID 34222025, 2021). "By immunohistochemistry analysis, we detected the expression of TSPAN1, Ki67, and the phosphorylation of AKT in tumor tissues, and found the decrease in TSPAN1 and Ki67 expression and the phosphorylation levels of AKT in TSPAN1-depleted tumor tissues." (PMID 34852709, 2021). "Interestingly, parts of genes, such as TSPAN1 and TRIM28, had higher accessibility of enhancer region in GBM compared to LGG and were significantly upregulated in tumour tissue than normal brain tissue." (PMID 38685685, 2024).